APOE (apolipoprotein E)
Diseases named in the same sentence as APOE in open-access papers (continued):
Sharing a sentence is not in itself a finding about the gene and the disease.
Insulin resistance (continued). "Other experiments demonstrated that activation of PPARγ ligands by rosiglitazone attenuated pulmonary hypertension via suppressing oxidative, insulin resistance, and proliferative signals in mouse models treated with chronic hypoxia or apoE knockout mice fed a high-fat diet." (PMID 34765605, 2021). "A limitation in our study is the fact that we did not account for the APOE-ε4 of hosts who, due to increased insulin resistance markers, are more susceptible to both the positive and negative biological effects of fatty acids in response to dietary changes." (PMID 32732956, 2020). "The reduction in the expression of apoE and other proteins in this network may also contribute to the pro-atherogenic role of IFNγ, especially in the setting of insulin resistance." (PMID 31231209, 2019). "High dose of insulin also improved peripheral insulin resistance in APOE positive patients." (PMID 26136647, 2015). "This could be easily tested by treatment of Eln +/−;ApoE −/− mice with anti-hypertensive drugs to see if insulin-resistance can be prevented or reversed." (PMID 26167199, 2014). "Defects in insulin secretion but not insulin resistance explain the susceptibility of B6.apoE-/- mice to diet-induced T2DM." (PMID 22204493, 2011). "Thus we postulate that insulin resistance measured by TyG index might contribute to BBB damage in APOE ε4 carriers as a result of a low chronic inflammation status, which will need to be tested in larger studies." (PMID 39992249, 2025). "Thus, LRP1‐ induced BBB integrity damage might represent the possible mechanism linking APOE genotype and insulin resistance." (PMID 39992249, 2025). "In addition, APOE ε is mainly produced by the liver, but can also be synthesized in and regulate the activity of adipocytes which might explain the relationship between APOE ε4 and insulin resistance." (PMID 38509472, 2024). "As brain insulin resistance can be observed many years before the onset of cognitive symptoms in AD, we investigated whether the brains of the mice with humanized APOE ε4/ε4 livers exhibited changes in key markers of the insulin signaling pathway in the cortex and hippocampus." (PMID 35418601, 2022). "Additionally, none of these studies accounted for APOE or other genetic risk factors, life-style factors, or the severity of diabetes and the degree of insulin resistance and glycemic control." (PMID 34220427, 2021). "This suggests that TMP may ameliorate insulin resistance in ApoE−/− mice fed with a high-fat diet." (PMID 28491104, 2017). "Thus, large epidemiological series have reported the association between insulin resistance or DM and the risk of AD, albeit independent of the APOE-4 phenotype." (PMID 25346723, 2014). "Insulin resistance is a common feature in non‐diabetic AD and correlates with altered BBB permeability, interacting synergistically with APOE genotype." (PMID 39992249, 2025). "In our previous study, oral LPS administration to ApoE KO mice fed a high-fat diet and P8 (SAMP8), a mouse model of accelerated aging, reduced insulin resistance and AUC during a glucose tolerance test." (PMID 36902049, 2023). "For the four proteins that differed between PCOS subjects and control women (ApoE, ApoM, C3, and HCFII), correlations with age; BMI; insulin resistance (HOMA-IR); testosterone; and circulating levels of TG, cholesterol, HDL-C, LDL-C, and CRP were performed." (PMID 36980195, 2023). "In this study, by using the ApoE−/− mice, we hypothesized that 1) the combination of HFD, hyperlipidemia, and adiponectin knockdown may cause more severe insulin resistance and 2) that the insulin resistance ameliorating effects of liraglutide was, at least in part, due to increased FGF-21 activity." (PMID 23152772, 2012).
Insulin resistance (continued). "As for the role of APOE in the development of CAD in DM patients, it may be related to inflammatory response, oxidative stress, insulin resistance and other mechanisms." (PMID 38491412, 2024). "Intranasal insulin detemir exerted better action in the hypothalamus and reduced peripheral insulin resistance in individuals who are APOE ε4 negative or obese, as compared to regular insulin." (PMID 38441832, 2024). "Controlling cortical thickness and intracortical myelin variability mitigated these APOE effects on PI, with no similar adjustment made for insulin resistance." (PMID 39656485, 2024). "In fact, the occurrence of insulin resistance is greatest in adults with AD who are APOE-ε4 non-carriers." (PMID 37379265, 2023). "Therefore, insulin resistance decreases glycogen storage, inhibits astrocyte proliferation, decreases glucose influx into the brain due to reduced GLUT1 expression, and increases ApoE expression." (PMID 36834911, 2023). "In addition, several energy metabolic processes, such as the PI3K-Akt pathway (EPHA2, FLT4, ITGA5, and LPAR6), cholesterol metabolism (APOE and CD36), and insulin resistance (FOLR1, CALM14, and PPP1R3A), were enriched in ApoE4 mice." (PMID 36720919, 2023). "ApoE and 8 other members of this macrophage protein network were dysregulated in the presence of insulin resistance via a mechanism dependent on IFNγ and independent of changes in their transcript levels." (PMID 31231209, 2019). "We also determined insulin resistance in the brain by quantifying phosphorylated form of IRS protein and observed a significant decrease in p-IRS protein levels with genistein supplementation in ApoE−/− mice." (PMID 27809235, 2016). "Conversely, high dose of insulin experienced increased peripheral insulin resistance in APOE negative patients." (PMID 26136647, 2015). "These potential biomarkers of insulin resistance increased significantly from normal cases, through mild cognitively impaired cases, to frank AD cases, regardless of APOE-4 status." (PMID 25346723, 2014). "Despite the fact that BALB.apoE-/- mice displayed significant insulin resistance on the Western diet, as evidenced by the lack of insulin response during the insulin tolerance test, they did not develop hyperglycemia." (PMID 22204493, 2011). "In the first study, our data shows diet-induced insulin resistance reduces tau phosphorylation at 3 epitopes, independent of APOE genotype." (PMID 21347323, 2011). "This study demonstrates that defects in insulin secretion rather than defects in insulin resistance explain the marketed difference in susceptibility to T2DM in the B6.apoE-/- and BALB.apoE-/- mouse model." (PMID 22204493, 2011). "In order to investigate TG intolerance caused by a variety of factors including heterozygous LPL-deficiency, insulin resistance, noninsulin-dependent diabetes mellitus (NIDDM), and ApoE isoforms we determined ApoE genotypes, and HL and LPL activities." (PMID 21609439, 2011). "In conclusion, diet-induced insulin resistance appears to induce changes in tau phosphorylation due to peripheral hyperinsulinemia independent of APOE genotype." (PMID 21347323, 2011). "On the other hand, B6.apoE-/- mice did not have insulin resistance, as indicated on the insulin tolerance test, but they developed hyperglycemia, suggesting that a defect in insulin secretion is essential for the development of hyperglycemia in this model." (PMID 22204493, 2011). "However, in the absence of insulin resistance and significant changes in dyslipidemia, they developed comparable levels of aortic plaques to their ApoE−/− controls." (PMID 35457157, 2022). "Because NASH develops in parallel to adipose tissue dysfunction, type 2 diabetes, and insulin resistance in humans and other mouse models, we assessed weight gain and the morphological and molecular profiles of gonadal white adipose tissue obtained from HFHCD-fed ApoE KO and DKO mice." (PMID 32796650, 2020).
Insulin resistance (continued). "These investigations suggest that reduced expression of KLF4 triggered by a high-fat diet in our mouse model (IR+/-IRS1+/-ApoE-/-) may mediate down-regulation of IRS2 and TSC2 expression thereby impairing insulin signaling in adipocytes and promoting insulin resistance." (PMID 30240435, 2018). "In term of metabolism, there was no beneficial effect of training on either insulin resistance (as shown both in plasma and muscle, with even an aggravation of systemic insulin resistance in EX ApoE−/− mice), or body composition (as assessed by the fat content measured by MRI) in old ApoE−/− mice." (PMID 27766082, 2016). "Even though adults' GD I present peripheral insulin resistance, reduced HDL-cholesterol, increased triglyceride and apolipoprotein E plasma levels, no increased incidence of type 2 diabetes and premature atherosclerosis was reported." (PMID 41425985, 2025). "RCS analysis indicated non-linear and dose response relationships between APOE, AHI, ODI, MAI and insulin resistance." (PMID 38956564, 2024). "Previously, we established a mouse model (ApoE-/-/miR155-/-; DKO mouse) of MHO, based on the criteria of not having metabolic syndrome (MetS) and insulin resistance (IR)." (PMID 33488632, 2020). "Since it is not yet clear how apoE isoforms influence the development of T2DM and its progression to AD, we investigated amyloid beta and tau pathology in APOE knockout mice, carrying human APOEε3 or ε4 transgenes after diet-induced insulin resistance with and without pioglitazone treatment." (PMID 21347323, 2011).
type 2 diabetes (163 papers, 2005 to 2026). "These associations were more pronounced in APOE ε4 carriers and in participants with type 2 diabetes." (PMID 38218902, 2024). "It is possible that PPARGC1A genetic variation, which is also associated with Parkinson’s disease, CHD, and type 2 diabetes can affect its binding with target transcription factors and thus expression of many genes, including APOE." (PMID 37666928, 2023). "Stratified analyses for APOE ε4 were therefore carried out between PRS 1–7 for type 2 diabetes and all-cause and vascular dementia." (PMID 37091584, 2023). "Our results also support a strong trend of APOE ε2 allele as a protective factor toward DM, with a reduction of type 2 diabetes odds by 66% in carriers of that allele (OR = 0.342; p = 0.093)." (PMID 39081475, 2022). "Regarding genetic factors, a significant association of ApoE polymorphism was found with poor recovery from a posttraumatic coma and, lately, with the diagnosis of prolonged UWS." (PMID 35295839, 2022). "SEM suggested that type 2 diabetes, age, and the ApoE ε4 allele (ApoE-ε4) can affect cognition via reduced subcortical structure volumes (total effect: age > ApoE-ε4 > type 2 diabetes)." (PMID 35173604, 2022). "Several studies have remarked the role the apolipoprotein E allele 4 (APOE4) as a common risk factor for AD and type 2 diabetes." (PMID 34778340, 2021). "Although the cause of AD is unclear, several studies have reported that age, family history, the ε4 allele of apolipoprotein E (APOE), high cholesterol, type 2 diabetes, and cardiovascular disease are associated with the development of AD." (PMID 34884818, 2021). "The relationship of APOE polymorphism with the risks of nephropathy in type 2 diabetes (T2DN) remains elusive." (PMID 32534589, 2020). "In combination, MASP, adiponectin and apoE improved type 2 diabetes prediction beyond non-invasive risk factors or HbA1c, age and sex." (PMID 30599058, 2019). "The purpose of the study was to evaluate the relationship between ApoE genetic polymorphism and the presence of DN in Chinese type 2 diabetic patients." (PMID 28326331, 2017). "In summary, we observed an association between the ApoE polymorphism and DN in Chinese type 2 diabetes patients." (PMID 28326331, 2017). "Most patients with AD have a sporadic, late onset form, where the major risk factors are aging, type 2 diabetes (T2D) and apolipoprotein E ε4 (APOE-ε4)." (PMID 27240327, 2016). "We recently have found that apolipoprotein E-deficient (Apoe-/-) mice with the C57BL/6 background develop type 2 diabetes when fed a Western diet for 12 weeks." (PMID 25946019, 2015). "APOE promoter −491A/T, −219G/T and +113G/C genotype distributions and allele frequencies were similar between the control and type 2 diabetes groups." (PMID 22028770, 2011). "Since we previously reported an association between APOM gene polymorphism and the disease duration of type 2 diabetes, such association was also tested for the three APOE promoter SNPs." (PMID 22028770, 2011). "At physiological level, the genotype-function relationship of APOE promoter polymorphism was studied in type 2 diabetes." (PMID 22028770, 2011). "In this study we investigate the genotype-function relationship of APOE promoter polymorphism at molecular level and at physiological level: i.e., in transcription control of the gene and in the risk of type 2 diabetes." (PMID 22028770, 2011). "At physiological level, the association between the APOE promoter polymorphism and the risk of type 2 diabetes was tested for the −491A/T, as well as for two additional SNPs −291G/T and +113G/C." (PMID 22028770, 2011). "To investigate the genotype-function relationship of APOE promoter polymorphism at physiological level, we tested the association between APOE promoter SNPs and the risk of type 2 diabetes in Hong Kong Chinese." (PMID 22028770, 2011).
type 2 diabetes (continued). "At physiological level, no genotype-risk association was detected between the studied APOE promoter SNPs and type 2 diabetes in Hong Kong Chinese." (PMID 22028770, 2011). "In 630 cases and 595 controls, three APOE promoter SNPs −491A/T, −219G/T (rs405509), and +113G/C (rs440446) were genotyped and tested for association with type 2 diabetes in Hong Kong Chinese." (PMID 22028770, 2011). "We searched the public DIAGRAM type 2 diabetes GWAS data and found that the SNP in the ApoE locus was significantly associated with T2DM in European ancestry, with rs429358 as the leading SNP (p = 1.4 ×10−10, beta = 0.12, number of T2DM cases = 26,676, number of controls = 132,532)." (PMID 37123009, 2023). "Given that APOE is associated with Alzheimer’s and cardiovascular diseases and type 2 diabetes, comorbidities that are related to COVID-19 susceptibility and severity, the effect of the APOE variant on COVID-19 could be indirect." (PMID 36531218, 2022). "Besides, type 2 diabetes which is an established risk factor for AD, shares in common the deleterious consequences of the expression of apolipoprotein E allele 4 (ApoE4)." (PMID 35111799, 2021). "Type 2 diabetes is associated with increased APOE, BAX, MMP1, NFKB1, PDGFB, SPP1, and TGFB2." (PMID 35153741, 2021). "Moreover, miR-34a is upregulated in PBMCs from patients with type 2 diabetes, and in atherosclerotic plaques in humans and apoE deficient mice." (PMID 34371836, 2021). "The results of this study also clearly show that MASP together with apoE and adiponectin improves the prediction of type 2 diabetes on top of non-invasive risk factor variables and on top of age, sex, and HbA1c concentrations, which are well-known to have a high predictive power." (PMID 30599058, 2019). "Moreover, apolipoprotein E gene polymorphisms have been shown to be associated with the lipid profile and prevalence of type 2 diabetes." (PMID 23866006, 2013). "Associations between APOE polymorphisms and the risk of type 2 diabetes." (PMID 22028770, 2011). "Consequently, the loss of interhemispheric hippocampal asymmetry has emerged as a key contributor to cognitive decline and putative biomarker across various neurologic and neuropsychiatric conditions, including type 2 diabetes carriage of the ApoE ɛ4 allele, as well as in BD and MDD." (PMID 39980329, 2025). "In addition, we aimed to assess whether certain subgroups of participants, such as APOE ε4 carriers or persons with type 2 diabetes, might drive such associations." (PMID 38218902, 2024). "In this study, we fed ApoE−/− mice with high fat diet for 8 weeks and then intraperitoneally gave one low-dose injection of streptozotocin to successfully induce type 2 diabetes." (PMID 36059980, 2022). "Second, we conducted SEM analysis to extract the direct and indirect effects of type 2 diabetes, age, and ApoE-ε4 on major subcortical structural alterations, AD pathological biomarkers and cognition." (PMID 35173604, 2022). "Our results suggest that the effect of type 2 diabetes on cognition is much smaller than that of age and ApoE-ε4 (coefficient: age > ApoE-ε4 > type 2 diabetes)." (PMID 35173604, 2022). "A case-control study found that the ε2 and ε3 alleles, corresponding coding proteins E2 (Arg158 → Cys), and E3 (parent isoform) of Apolipoprotein E (APOE) influenced lipid profile, and gave rise to independent risk factors of DKD in type 2 diabetes." (PMID 34760900, 2021). "After adjustment for age, sex, waist and height (model 1), the levels of adiponectin were inversely and of apolipoprotein C-II (apoC-II), apoC-III, apoE, and MASP positively associated with incident type 2 diabetes." (PMID 30599058, 2019). "In combination with apoE and adiponectin, MASP improved the prediction of type 2 diabetes beyond non-invasive risk factor variables and beyond HbA1c, age, and sex." (PMID 30599058, 2019).